CALR (calreticulin)
Diseases named in the same sentence as CALR in open-access papers (continued):
Sharing a sentence is not in itself a finding about the gene and the disease.
rhabdomyosarcoma (2 papers, 2020 to 2022). A rare aggressive malignant mesenchymal neoplasm arising from skeletal muscle. "We showed that CAP induced the death of MX−7 mouse rhabdomyosarcoma cells with the hallmarks of immunogenic cell death (ICD): calreticulin and heat shock protein 70 (HSP70) externalization and high-mobility group box 1 protein (HMGB1) release." (PMID 32698492, 2020).
T-cell lymphoma (2 papers, 2020 to 2022). "Our results were in agreement with Zheng’s report illustrating CALR expression operates as an oncopromoter in T-cell lymphoma." (PMID 35264066, 2022).
Achalasia (1 paper, 2023). A disorder of esophageal motility characterized by the inability of the lower esophageal sphincter to relax during swallowing and by inadequate or lacking peristalsis in the lower half of the body of the esophagus. "C1QC+ macrophages also showed high upregulation of CALR in achalasia, a C1Q receptor gene that could contribute to microglial activation." (PMID 37542039, 2023).
adenomyosis (1 paper, 2013). The growth of endometrial tissue inside the muscular wall of the uterine corpus. "We present the observation of elevated IgG autoantibody to calreticulin associated with a case of adenomyosis." (PMID 26425587, 2013). "This single observation is intriguing and poses many questions about calreticulin’s role in the endometrium and the possible role of calreticulin autoantibodies in the immunological stress associated with adenomyosis." (PMID 26425587, 2013). "It is not known whether there is an association between the presence of calreticulin autoantibodies and the development of adenomyosis." (PMID 26425587, 2013). "Further study is required to determine whether there is a significant association between adenomyosis and the prevalence of calreticulin autoantibodies." (PMID 26425587, 2013). "A further study is required to determine whether there is a significant association between adenomyosis and the prevalence of calreticulin autoantibodies." (PMID 26425587, 2013). "It is possible that the presence of a high titer, blocking anticalreticulin autoantibody may reduce a key, but as yet unknown, endometrial regulatory function of calreticulin and increase the risk that adenomyosis might develop." (PMID 26425587, 2013). "It is also possible that the expansion of endometrial glandular tissue, as well as elevated estrogens, during adenomyosis may be associated with elevated expression of calreticulin, which induces an autoimmune reaction." (PMID 26425587, 2013). "It is also possible that the expansion of endometrial glandular tissue, as well as elevated estrogens, during adenomyosis may lead to elevated calreticulin, which induces an autoimmune reaction to it." (PMID 26425587, 2013).
adenovirus infections (1 paper, 2024). "A similar upregulation of calreticulin post adenovirus infections have been reported." (PMID 38494863, 2024).
adrenocortical adenomas (1 paper, 2013). "By immunohistochemistry, two biomarkers calreticulin and prohibitin were validated to be overexpressed in ACC compared with adrenocortical adenomas (ACA) and normal tissues, but also calreticulin overexpression was significantly associated with tumor stages of ACC." (PMID 23587357, 2013). "Expression patterns of three differently expressed proteins calreticulin, prohibitin and HSP60 in ACC, adrenocortical adenomas (ACA) and normal adrenocortical tissues were further validated by immunohistochemistry." (PMID 23587357, 2013).
brain cancer (1 paper, 2021). A primary or metastatic malignant neoplasm affecting the brain. "One-way ANOVA-based differential 2D-DIGE analysis identified significantly changed abundances of two P4HB, five CALR spots and one spot of HSPA5 in platelets between patients with lung and brain cancer and matched healthy controls." (PMID 34066760, 2021).
brucellosis (1 paper, 2025). Brucellosis is a bacterial infection that spreads from animals to people via unpasteurized dairy products or by exposure to contaminated animal products or infected animals.
carcinoma in situ (1 paper, 2020). "Immunostaining for CALR was more evident in the GLLP group on both PND 21 and PND 540 compared to the CTR group mainly in areas of carcinoma in situ." (PMID 33049715, 2020).
celiac disease (1 paper, 2009). An autoimmune genetic disorder with an unknown pattern of inheritance that primarily affects the digestive tract. "Immune reactivity to other autoantigens, including transglutaminase 3, actin, ganglioside, collagen, calreticulin and zonulin, among others, has also been reported in celiac disease." (PMID 19220902, 2009).
chronic heart failure (1 paper, 2025). "Further studies may evaluate the presence of calreticulin in chronic heart failure with significant fibrosis to better explain the role of this protein in naturally occurring diseases." (PMID 40564271, 2025).
CLN6 disease (1 paper, 2021). "Finally, like conditioned medium collected from neural cells derived from CLN6 disease mice, urine collected from CLN6 disease sheep also contained abnormal amounts of calreticulin (CALR) and CTSB." (PMID 34870700, 2021). "In addition abnormal amounts of CALR and CTSB were detected in conditioned medium collected from cultured cells derived from CLN6 disease mice and in urine from CLN6 disease sheep." (PMID 34870700, 2021). "Collectively, these findings suggest that CALR and CTSB can be used as effective biomarkers for CLN6 disease, whereas APOE, CTSZ and HEXA might serve as effective biomarkers for multiple NCL subtypes." (PMID 34870700, 2021).
cyst (1 paper, 2020). A sac-like closed membranous structure that may be empty or contain fluid or amorphous material. "In this study, we investigated the calreticulin gene from cereal cyst nematode and demonstrated that the effector protein HaCRT1 was synthesized in the subventral esophageal gland and overcame the immunity defenses to promote cyst nematode parasitism." (PMID 33329646, 2020).
dengue (1 paper, 2016). "Salubrinal, a specific inhibitor of the PERK pathway, inhibits dengue-induced increase of calreticulin at 24 h post infection (HPI) but only barely reduces the high level of calreticulin induced by tunicamycin." (PMID 26938301, 2016).
developmental delay (1 paper, 2006). "Hence, the wavy characteristic of the calreticulin KO ventricular myofibrils is not a result of a developmental delay but is a result of a defect associated with calreticulin deficiency." (PMID 17112388, 2006).
diabetic foot ulcers (1 paper, 2019). "In conclusion, we believe that AuNPs–calreticulin nanocomposites could be therapeutic and have the potential to be effectively used in the treatment of diabetic foot ulcers, and should be further tested in a clinical setting." (PMID 30625974, 2019).
disc degeneration (1 paper, 2025). "Thus, calreticulin appears to be a critical regulator of nucleus pulposus cell function and a potential target for therapeutic strategies aimed at mitigating disc degeneration." (PMID 39944489, 2025).
emphysema (1 paper, 2021). "Thereby, two homotrimer SP-D (rSP-D) activated macrophages predominantly through CALR/p38 MAPK signaling pathway, consistent with the previous report, in which trimeric SP-D failed to correct the pulmonary phospholipid accumulation and emphysema characteristic of SP-D knockout mice." (PMID 34484184, 2021).
endometrial polyp (1 paper, 2021). A benign nodular lesion protruding above the surface of the endometrium. "To determine whether polypectomy influences the expression of implantation-related factors, we examined the effects of excision on the expression levels of the IGFBP1, IGFBP7, PTGS2, and CALR mRNAs in 27 patients with endometrial polyps." (PMID 34638846, 2021).
endometriosis (1 paper, 2022). The growth of functional endometrial tissue in anatomic sites outside the uterine body. "Expression of calreticulin in endometrial cells in women with endometriosis and the effects in the calreticulin/CD91 pathway warrant further study to confirm this paradigm." (PMID 35421980, 2022).
endothelial dysfunction (1 paper, 2024). In vascular diseases, endothelial dysfunction is a systemic pathological state of the endothelium (the inner lining of blood vessels) and can be broadly defined as an imbalance between vasodilating and vasoconstricting substances produced by (or acting on) the endothelium. "Similarly, CALR, encoding calreticulin, an endoplasmic reticulum stress marker, and MAP kinase kinase 7 (MAP2K7), a key upstream transducer of stress-activated protein kinase, have been evidenced as vital contributors to endothelial dysfunction in an oxidative stress environment." (PMID 39080630, 2024).
epilepsy (1 paper, 2021). A brain disorder characterized by episodes of abnormally increased neuronal discharge resulting in transient episodes of sensory or motor neurological dysfunction, or psychic dysfunction. "The overexpression of calreticulin in the hippocampal CA3 across the 3 rat models of epilepsy also regulates Ca+2 uptake and release by the ER30." (PMID 33859251, 2021). "An increase of ADPRC in both the CA1 and the CA3 regions and of calreticulin in the CA3 region was found across the 3 rat models of epilepsy." (PMID 33859251, 2021). "Higher expression levels were observed for ADPRC, calreticulin, LPAR3 and transgelin 3 across the 3 rat models of epilepsy." (PMID 33859251, 2021).
Ewing sarcoma (1 paper, 2024). A small round cell tumor that lacks morphologic, immunohistochemical, and electron microscopic evidence of neuroectodermal differentiation. "In Ewing sarcoma (ES), we found that tumor cells utilize dual mechanisms to evade macrophage clearance by simultaneously over-expressing CD47 and down-regulating cell surface calreticulin (csCRT), the pro-phagocytic signal." (PMID 38992659, 2024).
familial thrombocytosis (1 paper, 2020). Familial thrombocytosis is a type of thrombocytosis, a sustained elevation of platelet numbers, which affects the platelet/megakaryocyte lineage and may create a tendency for thrombosis and hemorrhage but does not cause myeloproliferation. "Moreover, impaired MPL protein expression appeared to be universal in the MPN since it was also associated with MPL and CALR mutations as well as with germline MPL SNP in the MPL distal CRHD causing familial thrombocytosis." (PMID 32479500, 2020).
female infertility (1 paper, 2015). Diminished or absent ability of a female to achieve conception. "Our results highlight the importance of CALR for female reproduction and suggest that compromised CALR function can lead to ovarian insufficiency and female sterility." (PMID 26388295, 2015).
fungal infection (1 paper, 2022). "Under osmotic or other abiotic stresses, CNX showed a highly reducible accumulation in the developing soybean roots, but a negative correlation between the calreticulin gene expression and the defense reaction development to the fungal infection was not reported." (PMID 35050051, 2022).
glycogen storage diseases (1 paper, 2006). "On the other hand, glycogen accumulation in ventricles of calreticulin KO resembles a mild form of glycogen storage diseases." (PMID 17112388, 2006).
helminth infections (1 paper, 2023). "Some studies have demonstrated that calreticulin from helminth infections, such as T. spiralis, Necator americanus and E. multilocularis, bind to C1q to interfere with the activation of the classical complement pathway." (PMID 37600806, 2023).
hemochromatosis (1 paper, 2025). A disorder of iron metabolism characterized by a triad of HEMOSIDEROSIS; LIVER CIRRHOSIS; and DIABETES MELLITUS. "Additionally, calreticulin (CRT), a key ER chaperone, protects against iron-induced oxidative stress and contributes to MHC-I assembly, potentially explaining its regulatory role in iron overload conditions such as hemochromatosis." (PMID 39867458, 2025).
Hypercholesterolemia (1 paper, 2020). An increased concentration of cholesterol in the blood. "In contrast, hypercholesterolemia in conjunction with IR increases both calreticulin levels and apoptosis Similarly, atorvastatin protects the heart from IR injury and downregulates ER stress proteins, including calreticulin." (PMID 32323496, 2020).
Hyperinsulinemia (1 paper, 2017). An increased concentration of insulin in the blood. "Furthermore, calreticulin, a C1QR, showed upregulated gene expression in the heavier co-twins and correlated positively with hyperinsulinemia and negatively with the genes involved in the insulin signaling route." (PMID 28559893, 2017).
Hyperthermia (1 paper, 2022). "Hyperthermia increases the amount of calreticulin in TME and consequently induces ICD.Hyperthermia increases the expression of IL‐6, IFN‐γ, and TNF‐α." (PMID 35908281, 2022).
Hypocalcemia (1 paper, 2011). An abnormally decreased calcium concentration in the blood. "This is likely the result of a partial inhibitory effect of calreticulin on 1,25(OH)2D binding to its receptor in the parathyroid glands in the presence of hypocalcemia and sHPT." (PMID 21747853, 2011).
IgA nephropathy (1 paper, 2025). "Immunohistochemistry confirmed reduced CALR protein expression in patients with IMN, whereas IgA nephropathy (IgAN) cases showed elevated expression." (PMID 40568201, 2025).
Incisional hernia (1 paper, 2019). An abdominal hernia that occurs at a site of weakness in the abdominal wall resulting from an incompletely-healed surgical wound. "Some proteins including RNA polymerase III transcription factor, calreticulin, estrogen receptor 1, and Harvey rat sarcoma viral oncogene homolog were found to be higher in cases of postsurgical incisional hernia." (PMID 31024927, 2019).
infertile (1 paper, 2021). "In conclusion, we have demonstrated that endometrial CALR may play a role in the formation of decidua and that polypectomy of infertile patients may result in the co-operative expression of endometrial factors associated with endometrial receptivity, including CALR." (PMID 34638846, 2021). "In addition, the expression levels of endometrial CALR and other implantation-related factors were compared in the endometrium of infertile patients before and after polypectomy." (PMID 34638846, 2021). "We also examined whether polypectomy, a procedure that could ameliorate infertility, alters the endometrial expression levels of CALR and several implantation factors in women diagnosed as infertile." (PMID 34638846, 2021). "Thus, endometrial CALR may play a role in the formation of decidua, and the polypectomy of infertile patients may result in the co-operative expression of endometrial factors, including CALR, that could enhance endometrial receptivity." (PMID 34638846, 2021).
influenza (1 paper, 2022). An acute viral infection of the respiratory tract, occurring in isolated cases, in epidemics, or in pandemics; it is caused by serologically different strains of viruses (influenzaviruses) designated A, B, and C, has a 3-day incubation period, and usually lasts for 3 to 10 days. "Although CANX/CALR are typically considered to be ER/Golgi specific, these different viruses bud from different cellular compartments including the cell membrane (influenza, rabies, and HIV-1), nuclear envelope (HSV-1), multivesicular bodies (HBV), and ERGIC (Coronavirus)." (PMID 36149962, 2022). "In addition, both CANX and CALR are thought to contribute to human immunodeficiency/HIV type-1 (gp160) and influenza because of their impact on both HA and neuraminidase glycoproteins." (PMID 36149962, 2022).
invasive breast carcinoma (1 paper, 2022). A carcinoma that infiltrates the breast parenchyma. "What is more, the co-transfection of Ad-CALR significantly reduced the suppression of miR206 on invasive breast cancer stem cells." (PMID 36136972, 2022).
irritable bowel syndrome (1 paper, 2024). Irritable bowel syndrome (IBS) is a chronic functional condition of the lower gastrointestinal (GI) tract characterized by abdominal pain or discomfort and disordered bowel habit (diarrhea, constipation, or fluctuation between the two). "The assessment of fecal calreticulin could be utilized as an initial diagnostic tool for individuals presenting symptoms of irritable bowel syndrome or gastrointestinal issues associated with irritable bowel syndrome." (PMID 38666855, 2024).
ischemic heart disease (1 paper, 2020). "We demonstrate that calreticulin upregulation in the context of ischemic heart disease, in vitro hypoxia, and direct induction of ER stress may play an important role in the activation of apoptotic cell death pathways." (PMID 32323496, 2020). "To identify whether this increase is found in human tissue, we examined samples acquired from patients with ischemic heart disease, and measured calreticulin mRNA." (PMID 32323496, 2020).
liposarcoma (1 paper, 2019). A usually painless malignant tumor that arises from adipose tissue. "They found that calreticulin was frequently overexpressed in dedifferentiated areas of dedifferentiated liposarcomas compared with that in normal surrounding tissue." (PMID 30974841, 2019).
low grade glioma (1 paper, 2018). A grade I or grade II glioma arising from the central nervous system. "Moreover, TCGA analysis for CALR expression in both GBM and low-grade gliomas (LGG) showed that of the 591 sequenced GBM samples, only three (0.5%) patients demonstrated genetic alteration of CALR." (PMID 29443896, 2018).
malignant pleural mesothelioma (1 paper, 2022). A malignant neoplasm that arises from mesothelial cells in the pleura and shows a diffuse growth pattern. "Authors demonstrated that after prolonged (6 days) incubation in the presence of 250 nM JQ1, the malignant pleural mesothelioma (MPM) cells, but not normal non-transformed mesothelial cells (HMC) displayed elevated expression of the “eat-me” signals, calreticulin and ERp57." (PMID 36613460, 2022).
malnutrition (1 paper, 2020). Inadequate nutrition resulting from poor diet, malabsorption, or abnormal nutrient distribution. "The cluster formed CALR, HSPA5, P4HB and, PDIA6 is a potential indicator of maternal malnutrition on the endoplasmic reticulum dysfunction in the prostate of offspring since they act as the fundamental molecular machinery for correct protein folding and Ca2+ homeostasis." (PMID 33049715, 2020).
monocytic leukaemia (1 paper, 2017). "The DAMPs calreticulin and HMGB1 were expressed on cell surfaces of the human monocytic leukaemia cell line THP-1, after co-culturing with ABAs." (PMID 29181774, 2017).
myositis (1 paper, 2010). "Calreticulin immunoreactivity also appeared to distribute to a larger fiber population in biopsies of Group I and Group II myositis patients than that one of healthy subjects, whereas staining of biopsies of Group III patients was comparable with that of Group 0 subjects." (PMID 20334640, 2010). "Nonregenerating myofibers of myositis patients differed in immunoreactivity for Grp75 and calreticulin, although none of the patients studied showed an immunoreactivity pattern compatible with intracellular aggregates." (PMID 20334640, 2010). "Increased expression of Grp94 and calreticulin characterized patients with a high percentage of regenerating myofibers; experimental studies showed that this ER stress-response occurred simultaneously with myotube maturation, therefore lacking specificity for myositis." (PMID 20334640, 2010).
neuroectodermal tumour (1 paper, 2007). "The ER stress genes ERdj5, ERp57, GRP78, calreticulin and calnexin were induced in neuroectodermal tumour cells by fenretinide." (PMID 17353921, 2007).